PTPN11 (protein tyrosine phosphatase non-receptor type 11)
Diseases named in the same sentence as PTPN11 in open-access papers (continued):
Sharing a sentence is not in itself a finding about the gene and the disease.
gastric cancer (44 papers, 2009 to 2026). A primary or metastatic malignant neoplasm involving the stomach. "Some GWASs have demonstrated an association between the PTPN11 gene and gastric cancer, colitis, and serum lipid levels." (PMID 30096757, 2018). "In the present study, 5 htSNPs of the PTPN11 gene were investigated for their associations with H. pylori infection, gastric atrophy and gastric cancer in Chinese Hans population." (PMID 22788847, 2012). "This study aimed to investigate the association of haplotype tagging SNPs (htSNPs) in the PTPN11 gene encoding SHP-2 with gastric atrophy and gastric cancer in Chinese population." (PMID 22788847, 2012). "For example, Src homology region 2-containing protein tyrosine phosphatase 2 (Shp2), encoded by PTPN11, plays an important role in signal transduction downstream of growth factor receptor signaling, and is associated with various cancer types, including gastric cancer." (PMID 32041355, 2020). "This study aimed to confirm the formerly reported association between the PTPN11 polymorphism (rs2301756) and gastric atrophy measured with serum pepsinogens in a large number of Japanese subjects, as well as to examine the association with gastric cancer risk." (PMID 19589142, 2009). "In the two-way analyses involving PTPN11, PTPN11 rs12229892 showed a significant interaction with IL1B rs1143623, influencing gastric cancer risk (P value for interaction = 0.034, interaction index = 1.64)." (PMID 26158864, 2015). "Individual genetic effects of 13 single nucleotide polymorphisms (SNPs) in PGC, PTPN11, TLR4, and IL1B on the susceptibility to gastric cancer and atrophic gastritis have been reported in our previous studies." (PMID 26158864, 2015). "In this study, we found new SNP interactions among H. pylori-related host genes PGC, PTPN11, and IL1B modifying the susceptibility to atrophic gastritis and gastric cancer." (PMID 26158864, 2015). "The PTPN11 gene, which encodes SHP2, has been reported to be associated with helicobacter pylori-related gastric atrophy and gastric cancer." (PMID 23672255, 2013). "The correlation between PTPN11 hypomethylation and the incidence of gastric cancer may be specific to male patients, alcoholic patients, patients with poorly differentiated tumors, and patients with TNM stage III+IV." (PMID 37056387, 2023). "Reports on PTPN11 have focused on the development and prognosis of diseases such as promyelocytic leukemia, myelodysplastic syndrome in children, ulcerative colitis, and gastric cancer." (PMID 35186229, 2022). "reveals that PTPN11 expression is elevated in gastric cancer with H. pylori infection." (PMID 35957898, 2022). "In the early stages of gastric carcinogenesis, CagA from H. pylori translocates into gastric epithelial cells, undergoes tyrosine phosphorylation, and binds to PTPN11 in the human gastric mucosa in vivo to form a complex which is thought to contribute to the development of gastric cancer." (PMID 35957898, 2022). "The phenomenon of an effect modification by H. pylori infection observed in the PTPN11 and PGC interaction may provide an important hint to help prevent gastric cancer by eradicating H. pylori in susceptible people." (PMID 26158864, 2015). "For PGC rs6912200 and PTPN11 rs12229892, TC/TT genotypes at rs6912200 and GA/AA genotypes at rs12229892 each conferred a reduced risk of gastric cancer and atrophic gastritis, but not if they were present together." (PMID 26158864, 2015). "Moreover, H. pylori infection status affected the ORs of three tagSNPs (PGC rs4711690, PGC rs6912200, and PTPN11 rs12229892) for the development of gastric cancer or atrophic gastritis." (PMID 26158864, 2015). "In another epistatic interaction, the IL1B rs1143623 GC/CC genotypes showed an association with a reduced gastric cancer risk only if the PTPN11 rs12229892 GA/AA genotypes were absent." (PMID 26158864, 2015).
gastric cancer (continued). "Genotype frequencies for PTPN11 rs2301756 polymorphism, age-sex adjusted odds ratios (ORs) and 95% confidence intervals (CIs) of gastric cancer relative to H. pylori infected subjects without gastric atrophy (HP-infected without atrophy)." (PMID 19589142, 2009). "To investigate how this polymorphism of PTPN11 contributes to the gastric carcinogenesis among the H. pylori infected subjects, we also calculated the OR of gastric cancer compared with H. pylori infected subjects without gastric atrophy." (PMID 19589142, 2009). "In addition, PTPN11 is hypomethylated in patients with gastric cancer, and PTPN11 hypomethylation may lead to the upregulation of PTPN11 transcripts." (PMID 37056387, 2023). "This study aimed to examine the formerly reported association of G/A PTPN11 (protein-tyrosine phosphatase, nonreceptor-type 11) polymorphism (rs2301756) with gastric atrophy, as well as the association with gastric cancer in a Japanese population using a large sample size." (PMID 19589142, 2009). "In summary, we observed novel SNP interactions among PGC, PTPN11, and IL1B which modified the risks of gastric cancer and atrophic gastritis and we provided important hints of effect modification by H. pylori infection on the cumulative effect of PGC rs6912200, PGC rs4711690, and PTPN11 rs12229892." (PMID 26158864, 2015). "For PTPN11 rs12229892 and IL1B rs1143623, rs1143623 GC/CC genotypes were associated with a reduced gastric cancer risk only in the absence of rs12229892 GA/AA genotypes." (PMID 26158864, 2015). "For instance, gastric cancer induced by H. pylori is high in East Asian countries, and cagA in East Asian strains of H. pylori is more effective than cagA from Western strains in activating the SHP2/PTPN11 phosphatase, which triggers the proproliferative kinase ERK1." (PMID 29945886, 2018).
glioma (43 papers, 2013 to 2026). A benign or malignant brain and spinal cord tumor that arises from glial cells (astrocytes, oligodendrocytes, ependymal cells). "Among previously not reported associations with overall survival were mutations in GATA3 and FANCE genes in colorectal cancer, mutations in gene PTPN11 in glioma, and mutations in RNF43, MSH6 and FBXW7 genes in endometrial cancer." (PMID 39277826, 2024). "Through the implementation of paired analysis, this study identified 4 of 314 (1.3%) individuals who harbored a germline PTPN11 variant associated with NS, of which 3 individuals were diagnosed with a glioma or glioneuronal tumor." (PMID 39309743, 2024). "However, to our knowledge, this is the first case of low grade glial neoplasm of the spinal cord harboring both H3 K27M and PTPN11 mutations." (PMID 35484611, 2022). "On review of the literature, we identified 27 patients with NS and PTPN11 mutations diagnosed with brain tumours; dysembryoplastic neuroepithelial tumour (n = 11), oligodendroglioma (n = 2), medulloblastoma (n = 1), low grade glioma (n = 9) and high-grade glioma (n = 4)." (PMID 36882706, 2023). "None harbored alterations within genes of the MAP kinase signaling pathway (e.g., BRAF, KRAS, NF1, and PTPN11) that are also common in pediatric gliomas." (PMID 36437415, 2023). "There is one report of high grade brainstem glioma harboring both PTPN11 and H3F3A mutations, as well as one patient in a cohort of pediatric glioma with co-occurrence of H3 K27M mutations and other alterations in the MAPK pathway, including in BRAF and FGFR1." (PMID 35484611, 2022). "In this report, we present a case of a low grade glial neoplasm occurring in the thoracic spinal cord which harbored both H3 K27M (H3F3A p.K28M) and PTPN11 (p.Q510H) mutations." (PMID 35484611, 2022). "Many of the changes we saw in GS are novel in the setting of glial tumors, including copy number amplification in LYL1 and mutations in PTPN11." (PMID 34162346, 2021). "Neither H3 K27M nor PTPN11 mutations are frequently found in spinal tumors, and furthermore neither are classically associated with low grade gliomas." (PMID 35484611, 2022). "Somatic PTPN11 mutations are relatively infrequent in low grade glial neoplasms and have not been previously reported in subependymomas." (PMID 35484611, 2022). "First, to investigate the role of SHP2 in BRAF V600E glioma, we transiently reduced SHP2 expression in BRAF V600E glioma cells using pooled siRNA targeting PTPN11." (PMID 40900823, 2025).
colon carcinoma (36 papers, 2008 to 2025). "Previous studies found that PTPN11 shRNA or CRISPR/cas9-mediated deletion prevented adaptive resistance to vemurafenib in BRAF mutant colon cancer." (PMID 37325052, 2023). "PTPN11 protects mice from intestinal inflammation in epithelial cells, while promotes colitis and colitis-driven colon cancer in macrophages." (PMID 35957898, 2022). "It is remarkable that suppression of PTPN11 confers sensitivity to BRAF inhibitors (used in cancer therapeutics) in colon cancer by blocking signaling from the receptor tyrosine kinases to the RAS–MEK–ERK pathway." (PMID 29518019, 2018). "In addition, inhibition or knockout of PTPN11 confers sensitivity to BRAF inhibition in BRAF mutant colon cancer." (PMID 38504984, 2024). "Additionally, a somatic mutation in the non-receptor PTP Shp2, encoded by the PTPN11 gene, has been detected in a single colon tumor with an increased frequency of somatic alterations, but without microsatellite instability." (PMID 19000305, 2008).
colorectal cancer (33 papers, 2007 to 2025). A primary or metastatic malignant neoplasm that affects the colon or rectum. "Several studies reported that gain-of function mutations of PTPN11 are correlated with NS, JMML, or colorectal cancer." (PMID 35802774, 2022).
liver cancer (33 papers, 2012 to 2024). An epithelial or non-epithelial malignant neoplasm that arises from the liver. "MiR-186 inhibits the development of liver cancer stem cells by controlling the expression of PTPN11." (PMID 37965067, 2023). "However, PTPN11 shows a tumor-suppressive function in liver cancer, suggesting that PTPN11 plays different biological roles in different tumor cells." (PMID 35802774, 2022). "Previous reports showed that PTPN11 worked as oncogene in liver cancer initiation." (PMID 33816273, 2021). "SHP2, also known as PTPN11, has been elucidated its crucial role in liver cancer stem cell expansion." (PMID 31623651, 2019). "Correlation between the miR-186 and PTPN11 expression in 60 clinical liver cancer samples was analyzed and a significant negative correlation was deduced (r=0.772, p<0.005)." (PMID 33816273, 2021). "The negative correlation was confirmed between miR-186 and PTPN11 in liver cancer tissue samples." (PMID 33816273, 2021).
glioblastoma (31 papers, 2011 to 2025). The most malignant astrocytic tumor (WHO grade IV). "In Ink4a/Arf-deficient glioblastomas, PTPN11 regulates the interaction of PI3K with PDGFRα and activates the downstream AKT/mTOR pathway, ultimately promoting tumorigenesis." (PMID 35957898, 2022). "Key phosphorylation events in the RAS/MAPK cascade (e.g., in PTPN11) have been identified as potential switches mediating oncogenic pathway activation in glioblastomas." (PMID 35778969, 2022). "In contrast, in recurrent glioblastoma patients that respond to PD-1 blockade, there is enriched expression of BRAF and PTPN11 activation mutations." (PMID 34440802, 2021). "The co-occurrence of PTPN11 and NF1 mutations may work together to promote the uncontrolled growth and proliferation of cancer cells in glioblastoma." (PMID 38418494, 2024). "The inhibitory tyrosine phosphorylation is reversed by the SHP-2/PTPN11 phosphatase, and pharmacological inhibition of SHP-2 suppresses ERK pathway activation and tumors in mouse glioblastoma models." (PMID 33562401, 2021). "Src homology domain-containing phosphatase 2 (SHP2) (PTPN11) is a non-receptor PTP, which regulates several of the RTK pathways known to be overexpressed in glioblastoma, including EGFR, FGFR and PDGFR." (PMID 21934682, 2011).
neuroblastoma (31 papers, 2011 to 2025). Neuroblastoma (NB) is the most common solid, extracranial childhood tumor. "This supports the notion that high expression and gain-of-function mutations at PTPN11 enable therapy resistance and recurrence in neuroblastoma." (PMID 34957126, 2021). "A prominent example of pro-oncogenic PTP in neuroblastoma is PTPN11, whose gene is mutated with relative frequency in high-risk neuroblastoma tumors and whose inhibition by both allosteric and catalytic inhibitors is under intense scrutiny in neuroblastoma experimental models." (PMID 34957126, 2021). "In addition, high expression of PTPN11 mRNA associates with poorer survival of high-risk neuroblastoma patients with MYCN amplification." (PMID 34957126, 2021). "As previously reported for neuroblastoma, the mutation frequencies were generally low, with ALK (9%), PTPN11 (3%) and ATRX (3%) mutations being the most common." (PMID 36175618, 2022). "In the high-risk neuroblastoma genome, there are few additional recurrent mutations other than ATRX (7.1% deletion, 2.5% mutation), or PTPN11 (2.9%)." (PMID 36185250, 2022). "For example, in each neuroblastoma tumour sample, a mutation was present in only one out of five putative driver genes—ALK, ATRX, PTPN11, MYCN or NRAS." (PMID 34434669, 2021). "ALK activation has been shown to increase PTPN11 phosphorylation at Y542 and Y580 in a neuroblastoma cell line." (PMID 34569154, 2021). "Mutations in the RAS pathway occur frequently in neuroblastoma, not only in the RAS gene itself, but also through mutations in regulatory proteins and downstream signaling components (e.g., NF1 and PTPN11) or by triggering constitutive activation of the receptor kinases of the pathway (e.g., ALK)." (PMID 40115016, 2025). "It was found that the frequency of mutations in the RAS-MAPK signaling pathway was significantly increased in relapsed neuroblastoma tumors, including mutations in ALK, NF1, BRAF, PTPN11, FGFR1, and the three RAS genes, and that the mutations in this pathway were mutually exclusive." (PMID 40115016, 2025). "The protein tyrosine phosphatase SHP2 (encoded by PTPN11) mediates the activation of the MAPK and PI3K signaling cascades, and pharmacologic inhibition or depletion of SHP2 suppresses tumor growth in several cancer models, including neuroblastoma." (PMID 38032104, 2023). "It was shown that inhibition of PTPN11 might be an effective strategy to overcome NRAS-dependent resistance in neuroblastoma or KIT-induced myeloproliferative diseases." (PMID 37384296, 2023). "In relapsed neuroblastoma cases, mutations are more frequently observed in ALK, as well as other well-known oncogenes and tumor suppressor genes, such as NF1, RAS, and RAF, and also PTPN11 and FGFR." (PMID 34885007, 2021). "Additionally, other important genetic markers for neuroblastoma are mutations in ALK, PTPN11, TERT, ATRX, and amplification of MYCN." (PMID 34885007, 2021). "The phosphatase, PTPN11/SHP-2, which was also prominently detected in neuroblastoma endosomes may also be part of this complex." (PMID 25884760, 2015). "The most frequently harbored alterations of specific genes in neuroblastoma include heritable mutations in the ALK and PHOX2B observed in familial neuroblastoma, chromatin remodeling genes like ATRX, ARID1A and ARID1B and other important genes like PTPN11, MYCN, and NRAS." (PMID 37274289, 2023). "The possibility exists that ALK and PTPN11 are direct substrates of PTPN1 and PTPN2 in neuroblastoma cells." (PMID 34957126, 2021).
myeloproliferative neoplasm (30 papers, 2009 to 2025). A clonal hematopoietic stem cell disorder, characterized by proliferation in the bone marrow of one or more of the myeloid (i.e., granulocytic, erythroid, megakaryocytic, and mast cell) lineages. "Children with germline PTPN11 mutations are at increased risk for the development of a characteristically transient JMML-like myeloproliferative disorder in infancy classified as Noonan Syndrome-associated Myeloproliferative Disease (NS-MPD)." (PMID 39123476, 2024). "Expression of oncogenic PTPN11 in the hematopoietic compartment causes myeloproliferative neoplasm (MPN) in humans and mice." (PMID 25289670, 2014). "In mouse models, PTPN11 mutations cause a myeloproliferative disorder (MPD) but a more recent study showed that the PTPN11 E76K mutation was clearly sufficient to induce acute leukemia and this residue is commonly mutated in ALL." (PMID 25009801, 2014). "Conversely, patients with germline mutations in PTPN11 (NS) develop a myeloproliferative disorder that strongly resembles JMML, though nearly all cases appear to spontaneously regress over the first 18 months of life without a need for HCT." (PMID 24734223, 2014). "Conversely, expression of leukemogenic alleles of Ptpn11, such as Ptpn11D61Y or Ptpn11E76K, in the hematopoietic compartment results in a fatal myeloproliferative neoplasm (MPN), featuring leukocytosis, anemia and hepatosplenomegaly." (PMID 25289670, 2014). "Recent studies have shown that PTPN11 gain-of-function mutations induce cytokine hypersensitivity in myeloid progenitors and myeloproliferative disease with some similarity to JMML in mice, establishing the causal role of PTPN11 mutations in the pathogenesis of JMML." (PMID 22162691, 2012).